IGF1R (insulin like growth factor 1 receptor)
Diseases named in the same sentence as IGF1R in open-access papers (continued):
Sharing a sentence is not in itself a finding about the gene and the disease.
cancer (continued). "In general, IGF-1R is overexpressed in most solid tumors, and its expression is significantly associated with poor prognosis in cancer patients." (PMID 34359752, 2021). "In the same type of cancer, miR-342-3p can inhibit cell proliferation through the suppression of the IGF-1R-associated Warburg effect." (PMID 33768092, 2021). "Generally, IGF-1R is overexpressed in most solid tumors, and its expression is significantly associated with poor prognosis in cancer patients." (PMID 34359752, 2021). "The activity of the type I insulin-like growth factor receptor (IGF1R) has been linked to aggressive cancer growth and spreading, and inhibiting IGF1R activity has slowed cancer growth in laboratory models." (PMID 34191793, 2021). "High levels of IGF-1 are, in fact, associated with an increased incidence of several cancers, including colorectal, prostate and breast cancers, while mutations in the human IGF-1R were found to protect against age-related disorders." (PMID 34572814, 2021). "More recently, suppression of IGF1R signaling was found to affect mitochondria dynamics, causing the accumulation of elongated mitochondria in cancer cell lines." (PMID 33562061, 2021). "The IGF-1R elevated expression has also been associated with inhibition of apoptosis and increased proliferation rate and angiogenesis in patients with cancer." (PMID 34239447, 2021). "Regarding the role of IGF1R gene variant rs2229765 in cancer development, the current understanding remains controversial." (PMID 34501407, 2021). "IGF-1R is the receptor for both IGF-1 and IGF-2, and several oncogenes targeting IGF-1R transcription have been reported to cause the overexpression of IGF-1R in cancers." (PMID 33669204, 2021). "IGF-1R overexpression is associated with an enhanced growth rate of cancer cells, and studies have shown that patients with advanced clinical stages of PDAC (stages II and III) have higher levels of IGF-1R and low IGFBP3, correlating with poor prognosis." (PMID 34440625, 2021). "Meanwhile, the association of IGF-1R signaling in promoting cancer stemness properties has also been demonstrated in cancers." (PMID 34359714, 2021). "Many pieces of evidence have indicated that an increased level of IGF-1R is associated with cell survival and proliferation, metastasis and cancer progression, anti-cancer drug resistance, and poor prognosis for patients." (PMID 34769108, 2021). "Ligand-activated signaling through the type 1 insulin-like growth factor receptor (IGF1R) is implicated in many physiological processes ranging from normal human growth to cancer proliferation and metastasis." (PMID 33608571, 2021). "High expression of insulin-like growth factor 1 receptor (IGF-1R) is highly associated with cancer stemness and sorafenib resistance in HCC." (PMID 34359714, 2021). "Subsequent studies focusing largely on cancer mechanisms have shown that the activities of the αvβ3 and αvβ5 integrins and IGF-1R are linked and regulated by syndecan-1 (Sdc1)." (PMID 34778093, 2021). "The overexpression of IGF-1 and its receptor IGF-1R have been implicated in carcinogenesis and are also considered risk factors for the progression of diverse human cancers." (PMID 34804946, 2021). "Consistent with our results, IGF-1/IGF-1R signaling was reported to be associated with Hif-1α or Hif-2α expression in cancers and in cells of somatic lineage." (PMID 34381769, 2021). "Unlike other growth factor receptors, such as EGFR and HER-2, mutations activating the IGF-1R gene have rarely been reported in cancers." (PMID 34359752, 2021). "IGF-1R (insulin-like growth factor 1 receptor), a transmembrane receptor implicated in insulin signaling, plays a role in several cancer development." (PMID 34439182, 2021). "It has been suggested that under pathological conditions like cancer, the IGF-1R associates with a range of other receptor and signaling complexes at the plasma membrane." (PMID 33584548, 2020).
cancer (continued). "The IGF-1R pathway has been implicated as participating in the regulation of cell proliferation and antiapoptosis in cancers." (PMID 33511137, 2020). "Similar to other strategies for improving target therapy, one of the approaches is to identify biomarkers to select a suitable subgroup of cancer patients more susceptible to the treatment of IGF1R inhibitor." (PMID 32570949, 2020). "We developed dual degrader PROTACs to target both IGF-1R and Src, which are associated with various cancer cells." (PMID 32340152, 2020). "Under these conditions, the chronically increased insulin levels associate with increased cancer risk and to parallel increase levels in IR and Insulin-like Growth factor I (IGF1R)." (PMID 33266015, 2020). "A focused PROTAC library was developed to degrade both IGF-1R and Src proteins, which are associated with various cancers." (PMID 32340152, 2020). "Since IGF1R/PCNA interaction was associated with better outcome in the two clinical cancer cohorts, we sought to identify its functional role in cell lines." (PMID 32701997, 2020). "Clinical studies have shown that increased IGF-1R activity is implicated in activated cancer cells proliferation, migration and invasion." (PMID 32545325, 2020). "Some studies have also determined an increased IGF-1R activity to be implicated in cancer cell invasion, migration, and proliferation." (PMID 32498447, 2020). "Over-expression of the IGF-1R is the most common findings associated with deregulated IGF signaling in human cancers." (PMID 31293973, 2019). "Several studies have shown that overexpression of the IGF-1 receptor (IGF-1R) constitutes a typical hallmark of the majority of cancer types." (PMID 31035970, 2019). "Elevated IGF1R signaling has been implicated in many cancers, but thus far strategies to inhibit IGF1R have proven ineffective." (PMID 30653502, 2019). "PALB2, ALDH1A3, and IGF1R were reported to show associations with sensitivity to mitomycin, stem cell markers, and cancer progression, respectively." (PMID 30719229, 2019). "We discussed a number of well-known miRNAs and lncRNAs that regulate IGF-1R signaling in DM and cancer, and further highlight the potential underlying molecular pathogenesis of their comorbidity." (PMID 31847392, 2019). "Here we concentrate on the most frequently reported miRNAs to linked to IGF-1R and summarize their function in DM/cancer comorbidity." (PMID 31847392, 2019). "The IGF1R gene is responsible for cell proliferation and survival and is expressed in many types of cancer cells; enhanced activation of IGF1R is also implicated in the resistance to chemotherapy in a hypoxic microenvironment." (PMID 30867905, 2019). "IGF-1R is implicated in many cancers and plays an essential role in cancer development and progression." (PMID 31166382, 2019). "Through receiving the acetylated IGF-1 signaling, IGF-1R is activated to regulate cancer-associated functions, such as the proliferation to promote cancer cell proliferation." (PMID 31217907, 2019). "IGF-1R pathways have been implicated in tumourigenesis, metastasis, and resistance to existing forms of cancer therapy in various cancers." (PMID 31676869, 2019). "Consistently, we found that IGF1R is over-expressed in cancer tissues and is associated with adverse outcomes in HNC patients receiving radiotherapy." (PMID 30642292, 2019). "In this review, we briefly summarize a number of well-known miRNAs and lncRNAs that regulate the IGF-1R in DM and cancer, respectively, and further discuss the potential underlying molecular pathogenesis of this disease association." (PMID 31847392, 2019). "As previously reported, IGF-1R expression has prognostic value, being negatively associated with cancer-related survival." (PMID 30231881, 2018).
cancer (continued). "Both the type I insulin-like growth factor receptor (IGF1R) and Src pathways are associated with the development and progression of numerous types of human cancer, and Src activation confers resistance to anti-IGF1R therapies." (PMID 29455661, 2018). "Increased IGF-1R activity is implicated in tumorigenesis and cancer cell invasiveness and previous reports have shown that IGF1R is one of the targets of miR-140-5p." (PMID 30559931, 2018). "It is conceivable that “loss-of-function” and “gain-of-function” mutation theory can clarify the role played by the IGF-1R gene in cancer." (PMID 30111747, 2018). "Cells expressing high levels of cell-surface IGF1R are expected to survive, a hallmark of cancer cells." (PMID 29455671, 2018). "Data from the cancer field showed that ER mutations which increase its activity enhance the association of ERs and insulin like growth factor 1 receptor (IGF-1R), and increase IRS-1 phosphorylation." (PMID 29988365, 2018). "The activation of IGF-1R upon ligand binding induces phosphorylation of an adopter protein insulin receptor substrate-1 (IRS-1) which is also linked to various cancer subtypes." (PMID 29787591, 2018). "Various studies have associated IGF-1R expression with poor outcome in patients with esophageal, gastric, oral, or cervical carcinomas." (PMID 30231881, 2018). "We evaluated the role of IGF2 signaling pathway in MRT cell proliferations, and also confirmed this hormone promotes cancer cell growth through stimulation of IGF1R and INSR, which is associated with activation of PI3K/AKT and RAS/ERK pathways." (PMID 28521298, 2017). "Since Src tyrosine kinase (Src) is implicated in the development of cancer metastasis, we sought to examine its recruitment and interaction with ERβ2 and/or IGF-1R on plasma membrane in E2-stimulated PC-3 cells." (PMID 28968951, 2017). "Third, whole genome transcriptome analysis revealed that CEA−/lo cells preferentially expressed several genes including CD44, IGF1R etc., which were previously reported to associate with development and cancer stem cell functions." (PMID 27813496, 2016). "Deregulated expression of the IGF1R gene after ionizing radiation is linked to genomic instability and increased cancer rates." (PMID 27446805, 2016). "Recent studies have shown that IGF-1R overexpression is linked with the raising risk of the development of various cancers including HCC." (PMID 27813495, 2016). "The abnormal activation of Insulin-like growth factor 1 receptor (IGF1R) signaling has been demonstrated to be associated with cell proliferation, apoptosis, angiogenesis and resistance in several cancers." (PMID 27105537, 2016). "Type I insulin-like growth factor receptor (IGF-1R) is a potential diagnostic and therapeutic biomarker of several cancers." (PMID 26919100, 2016). "This is in accordance with studies that associated 3129G > T in IGF1R (rs2016347) with cancer prognosis and treatment outcome." (PMID 26738606, 2016). "One candidate gene, IGF1R (Insulin-Like Growth Factor 1 Receptor, located on chromosome 15q26.3) is well known to be associated with cell growth and various cancers." (PMID 27060904, 2016). "Whilst specific mutation of the IGF-1R is rarely reported in the literature, a large proportion of cancers carry a PI3K mutation (or PTEN deletion), constitutively activating Akt." (PMID 25964779, 2015). "A functional IGF-1R caused anchorage-independent growth in various cancers and activated proliferation and survival signaling pathway." (PMID 26307972, 2015). "IGF-1R can be found associated with E-cadherin in cell–cell adhesion complexes of normal corneal epithelial cells and in several cancer cell types." (PMID 26191041, 2015).
cancer (continued). "Gefitinib treated cells displayed increased levels of phosphorylation in IGF-1R and Akt, indicating the intensified activation of this cancer-associated signaling pathway in Mahlavu cells." (PMID 26003166, 2015). "Overexpression of insulin-like growth factor-1 receptor (IGF-1R) in several cancers is associated with resistance to therapy." (PMID 25425114, 2015). "For several types of cancer, an abnormally high expression level of IGF-1R is associated with metastasis and resistance to therapy." (PMID 25425114, 2015). "The insulin-like growth factor receptor (IGF-1R) signaling pathway plays a critical role in cancer cell survival, causing resistance to numerous anticancer drugs." (PMID 26041671, 2015). "Gene expression databases have revealed that most cancers express both the gene encoding the insulin receptor and the gene encoding the IGF-1R." (PMID 24970814, 2014). "From the dissection of hsa05200 (pathway in cancer), we revealed four high-risk genes (IGF1R, IGF1, RAS, and BCL2) to be MG risk genes and simultaneously showed they contained miRSNPs in their 3′UTR regions." (PMID 25118158, 2014). "In fact, overexpression of IGF1R was found to be associated with increased mortality in most cancer patients due to enhanced potential for metastasis." (PMID 24809702, 2014). "According to the topological properties of MSSPN and detailed mechanism dissection, we revealed the potentially significant roles of hsa05200 (pathway in cancer), four high-risk genes (IGF1R, IGF1, RAS, and BCL2), and associated miRSNPs in MG." (PMID 25118158, 2014). "Population-based studies show that circulating IGF-I and IGFBP-3 concentrations as well as genes for IGF and IGF1R have been associated with longevity, cancer and common chronic diseases." (PMID 24392142, 2014). "Previous studies revealed that low IGF-1R expression is associated with de-differentiation of various human cancers, indicating that IGF-1R expression is lost when cells become more malignant." (PMID 24489919, 2014). "IGF-1R is implicated in the promotion of oncogenic transformation, growth and the survival of cancer cells." (PMID 24137330, 2013). "The IGFs have been implicated through IGF1R in the pathogenesis, cell proliferation, and cell survival of many cancers." (PMID 23962053, 2013). "Uncontrolled IGF1R signaling is an important hallmark of certain cancers and interfering with IGF1R signaling can help control malignancies." (PMID 23651613, 2013). "The novel finding of a nuclear localizing Hybrid-R provides a potential mechanism underlying the trafficking of IGF-1R to the nucleus that was recently reported in cancer cells." (PMID 22879999, 2012). "The data suggest that the level of N-linked glycosylated IGF1R/IR heterodimeric receptor is highly associated with sensitivity to anti-IGF1R antibody in cancer cells." (PMID 22438913, 2012). "Enhanced activation of the IGF1R has been recognized as a major cause of resistance against EGFR-targeted therapies in cancer cells of different origin." (PMID 22815959, 2012). "Although the effects observed were modest, these mutations represent the first activating mutations of IGF1R identified in human cancers." (PMID 22778948, 2012). "Cancer genome sequencing efforts have recently identified three somatic mutations in IGF1R: A1374V, a deletion of S1278 in the C-terminal tail region of the receptor, and M1255I in the C-terminal lobe of the kinase catalytic domain." (PMID 22778948, 2012). "Two of the cancer-associated IGF1R mutations studied in this paper (ΔS1278 and A1347V) fall in the C-terminus and one (M1255I) is in the C-terminal lobe of the catalytic domain." (PMID 22778948, 2012). "Another aspect on a unique role of IGF-1R in cancer is based on several recent findings that loss of suppressor oncogenes as well as activation of proto-oncogenes is related to IGF-1R function and activity." (PMID 15956962, 2005).
cancer (continued). "In addition, it was revealed that miR-139 also targets IGF-1R, and low levels of miR-139 are associated with cancer progression and metastasis." (PMID 41153350, 2025). "The control of the IGF-1/IGF-1R signaling pathway by microRNAs is essential for many physiological functions and is closely associated with the development, progression and response to treatment of several cancer types." (PMID 41153350, 2025). "Furthermore, cancer‐associated fibroblasts (CAFs)‐activated IGF1R/Akt/mTOR/c‐Myc pathway transcriptionally upregulates QSOX2 expression, establishing a QSOX2/mTOR feedback loop that sustains ESCC cell stemness." (PMID 40433832, 2025). "Various cancer types are associated with elevated levels of IGF1R and circulating IGF-1/IGF-2." (PMID 38791406, 2024). "Different mechanisms can influence IGF1R activity to produce cancer phenotypes, including (i) IGF1R overexpression caused by IGF1R gene aberrations, (ii) regulation of IGF1R expression by modifier genes, (iii) increased levels of ligands, and (iv) transactivation by other membrane receptors." (PMID 38791406, 2024). "Ongoing research is being conducted to understand the roles of hybrid IGF-1R/IR receptors in various diseases and cellular processes, which is crucial for unraveling the complexities underlying cancer initiation and progression, as well as informing the development of targeted therapies." (PMID 38540176, 2024). "IGF1R overexpression has been linked to the development of several cancers, including ovarian." (PMID 39450263, 2024). "Abnormal IGF-1R activation has been associated with cancer initiation and development." (PMID 38540176, 2024). "Additionally, the IGF1R pathway has been linked to resistance to several cancer treatments, including chemotherapy and targeted therapies, highlighting its potential as a therapeutic target for overcoming drug resistance." (PMID 37744271, 2023). "Autocrine IGF2 is also implicated in cancer resistance to IGF1R blockade." (PMID 36672737, 2023). "In other studies, treatments that target IGF-1R were found to sensitize cancer cells to irradiation, and kinase-deficient mutant IGF-1R cancer cells exhibited significantly decreased growth and viability and reduced clonogenic survival after irradiation compared with wild-type cells." (PMID 36831629, 2023). "The significant association between IGF1R and cancer results from IGF1R gain-of-function mutations." (PMID 38274107, 2023). "Various pathways lead to the resistance to IGF1R-targeted therapy, such as compensatory RTKs activation and alternative integrin signaling, and diverse factors dictate the susceptibility of cancer cells to IGF1R targeting, including oncogenic states and cell identities/states." (PMID 36774408, 2023). "Previous studies identified that various polymorphisms of the IGF1R gene could modify the susceptibility of cancer." (PMID 37284192, 2023). "We propose that comparable approaches aimed at developing agents targeting IGF-1R downstream signaling molecules specifically implicated in each type of cancer on a case-by-case basis could have better anticancer resistance effects with less toxicity." (PMID 36017326, 2022). "In addition, IGF1/IGF1-R was found to a target associated with the PI3K/AKT pathway in the depression of cancer proliferation, subcellular distribution, invasion, and chemoresistance." (PMID 35280511, 2022). "In sum, these data not only suggest that tumorally expressed IGFBP5 may serve as a useful marker to assess responsiveness of cancer cells to IGF1R inhibitors, but also that IGFBP5 is causatively involved in the acquisition of resistance to these drugs." (PMID 36093095, 2022).